SOX2 (SRY-box transcription factor 2)
Diseases named in the same sentence as SOX2 in open-access papers (continued):
Sharing a sentence is not in itself a finding about the gene and the disease.
melanoma (continued). "Melanoma stem cells, in particular, are characterized by the expression of embryonic transcription factors, including NANOG (Homeobox protein), Oct4 (octamer-binding transcription factor 4) and Sox2 (sex-determining region Y HMG-box 2)." (PMID 35847038, 2022). "First, we addressed whether phosphorylation at Ser251 could impact on the turnover of SOX2, as treatment with PLX4032 increased endogenous SOX2 stability in melanoma cells." (PMID 35944584, 2022). "NOP14 overexpression subsequently decreased the proportion of CD133+ SLCs, impaired the colony-forming capabilities, and downregulated the expression of Nanog, SOX2, and OCT4 stem cell markers in A375 and A875 cells, suggesting that NOP14 suppresses the stemness of melanoma SLCs." (PMID 35282769, 2022). "Conversely, recent studies revealed that malignant melanoma initiation and progression are not affected by complete inhibition of SOX2 function." (PMID 35719931, 2022). "The increased self-renewal ability induced by PLX4032 was also observed in melanoma cells overexpressing SOX2-WT, while overexpression of nonphosphorylated SOX2-S251A had the opposite effect, paralleling that of SOX2 depletion." (PMID 35944584, 2022). "Since CD24 expression can be induced by SOX2 in melanoma cells, we asked whether CD24 might be regulated by SOX2 in ECs as well." (PMID 34293822, 2022). "The increased self-renewal ability induced by BRAFi is also observed in melanoma cells overexpressing SOX2-WT, while overexpression of nonphosphorylable SOX2-S251A has the same effect of SOX2 depletion." (PMID 35944584, 2022). "In melanoma, both MEK and BRAF inhibition led to an induction of SOX2 that could be reversed by inhibition of DUB." (PMID 33613844, 2021). "Silencing of BRD4, as well as its pharmacological depletion with MZ1 or catalytic inhibition through JQ1, prevented SOX2-binding to GLI1 promoter, without altering SOX2 expression in melanoma cells." (PMID 33958721, 2021). "TMA using 12 samples from malignant patients and 7 normal/control tissues showed thehigher expression of SOX2 at protein level in melanoma tissues, in comparison with normalskin biopsies." (PMID 34308569, 2021). "We demonstrate that SOX2 induced by vemurafenib and MEK inhibitors may in part contribute to the high sensitivity of melanoma to DUB inhibition which leads to SOX2 depletion." (PMID 33613844, 2021). "Quantitative real-time PCR results showed that the PTBP1 silencing led to significant downregulations of stemness genes (Klf4, Nanog, Oct4, and Sox2) compared with the controls, indicating that PTBP1 played a positive role in maintaining the stemness of melanoma stem cells." (PMID 33149126, 2020). "We detected ISG.RS mRNA level in negative control or SOX2 KD melanoma cell lines and observed that SOX2 KD decreased the ISG.RS expression (IDO1, PDL1, IFI27, and USP16)." (PMID 33158915, 2020). "Dong Wei identified that ATF2, SOX2, and RAC1 are involved in the metastasis of melanoma." (PMID 33336008, 2020). "In the melanoma model, the IL-1β-stimulated B16-F10 cells expressed higher levels of Nanog (P = 0.002), SOX2 (P = 0.010), and OCT4 (P < 0.001) as compared with non-stimulated cells." (PMID 32547321, 2020). "Besides SOX2, the GLI transcription factors GLI1 and GLI2 have been suggested to be involved in melanoma progression and metastasis and to be responsible for maintenance of melanoma-initiating cells." (PMID 33203881, 2020). "Stem cell markers present in melanoma cells are nestin, CD133, CD271 and Sox2." (PMID 32899370, 2020). "Furthermore, ectopic expression of ST3GAL1 rescues the effect of SOX2 and/or GLI1 depletion on melanoma cell invasiveness." (PMID 33203881, 2020). "Indeed, TRIM28-depleted melanospheres expressed lower levels of stem cell markers, namely OCT-3/4 and SOX2, further supporting our observation of TRIM28-dependant regulation of stem-cell like population in melanoma." (PMID 33076560, 2020).
melanoma (continued). "Furthermore, protein levels of GLI1, SOX2, ST3GAL1, and AXL were analyzed in short-term cultures of primary and metastatic melanomas." (PMID 33203881, 2020). "In particular, in malignant melanoma, the expression level of miR‐625 was inversely correlated with that of transcription factor SOX‐2 (SOX2), suggesting that the anti‐tumor action of miR‐625 is at least partially mediated by the inhibition of SOX2." (PMID 30499222, 2019). "Consistently, no transplanted organoid cells corresponded to SOX2+ NTRK2+ neural precursors or PMEL+ melanoma-like cells." (PMID 31784515, 2019). "We thus concluded that transplantation abrogated SOX2+ neuronal and PMEL+ melanoma off-target cells, and may have promoted organoid maturation toward a more advanced human-like state." (PMID 31784515, 2019). "By studying non-acidic SSM2c and 501-Mel melanoma cells (high- and very low-SOX2 expressing cells, respectively), we confirmed the metabolic role of SOX2, attributing SOX2-driven OxPhos reprogramming to HIF1α pathway disruption." (PMID 30466459, 2018). "By RT-real time PCR analysis, we could observe that the expression of the embryonic transcription factors SOX2 and KLF4 is significantly increased in spheroid-derived cells, when compared to A375 adherent melanoma cells." (PMID 29330434, 2018). "Interestingly, modulation of SOX2 expression by PGF2α agonists and upregulation by fibroblast growth factor 1 (FGF-1) rescued melanoma cells from ASA-induced decreased survival and increased apoptosis." (PMID 28636992, 2017). "In addition to SOX10, SOX2—another member of the HMG-box transcription factor family—also plays an important role in the control of self-renewal and tumorigenicity of melanoma-initiating cells." (PMID 29156643, 2017). "CD271 knockdown was found to eliminate the capacity of melanoma cells to form heterogeneous tumors most likely through the downregulation of mediators for melanoma invasion and metastasis (GLI-2, SOX2 and ERBB3), angiogenesis (IGFBP-2), proliferation (FST and MITF) or chemoresistance (RHOJ)." (PMID 25351876, 2015). "Furthermore, it was discovered that by concurrently blocking the MAPK/c-Myc/cyclin D1 and STAT3/SOX2 pathways, a combination of DHT and MAPK pathway inhibitors could accelerate the death of melanoma cells." (PMID 39944829, 2025). "In other words, the non-essential role of SOX2 has also been found in melanoma, raising the possibility that there might be other cancer types where SOX2 does not function as well." (PMID 38334608, 2024). "In a recent model utilizing tumorigenic melanoma tumor-repopulating cells, high SOX2 (a member of the SOX transcription factors) levels fueled growth, low levels of SOX2 put cells into a state of dormancy, and a complete knockout of SOX2 exited the quiescent state into a less stem-like phenotype." (PMID 38426087, 2024). "Chromatin immunoprecipitation (ChIP) using anti-SOX2 antibody followed by qPCR revealed SOX2 occupancy in the proximal promoter region of ABCG2, with a 2- to 4-fold enrichment in SOX2 signal over ChIP with nonspecific IgG in two different melanoma cell types (p < 0.05)." (PMID 35944584, 2022). "Besides SOX2, GDF3 has been shown to stimulate CD24 expression in melanoma cells." (PMID 34293822, 2022). "This suggests that FMOD and SOX2 might regulate metastatic competence without altering the tumorigenic properties and highlights their functional specificity in melanoma BrM." (PMID 35737114, 2022). "Our data suggest a possible role of SOX2 in tumors with FMOD dysregulation; concomitant SOX2 upregulation might contribute to its association with the early development of melanoma BrMs, but not with disease aggressiveness." (PMID 35737114, 2022). "However, melanoma cells mainly have a high expression level of SOX2 while it is not observed in neural crest stem cells." (PMID 34768751, 2021).
melanoma (continued). "Although it is reported that SOX2 may start the tumor initiation process via CDK1 in melanoma, knocking-out of SOX2 by CRISPR-Cas9 does not affect melanoma progression and metastasis." (PMID 34768751, 2021). "However, other studies show that in mice SOX2 is not required for melanoma growth and metastasis in vivo." (PMID 33613844, 2021). "Interestingly, other members of the O-glycan biosynthesis pathway appear to be regulated by both SOX2 and GLI1, suggesting that these two TFs may promote melanoma progression through the induction of aberrant glycosylation." (PMID 33203881, 2020). "Indeed, ST3GAL1 appears to mediate the effects of SOX2 and GLI1 on melanoma cell invasion." (PMID 33203881, 2020). "In human melanoma, the interaction between CDK1 and SOX2 could promote tumorigenesis." (PMID 33178832, 2020). "Moreover, IL-1β stimulation promoted the stem-like capabilities of both HNSCC cells and melanoma cells, including the enrichment of aldehyde dehydrogenase+ (ALDH+) cells, up-regulation of stem cell related markers Nanog, OCT4, and SOX2, sphere formation and chemoresistance." (PMID 32547321, 2020). "Next, we asked whether ST3GAL1 could mediate SOX2- and GLI1-induced melanoma invasiveness." (PMID 33203881, 2020). "More recently, Lxn has been shown to inhibit melanoma cell proliferation and down-regulate the expression of several stem cell transcription factors, such as octamer-binding transcription factor 4 (OCT4), sex determining region Y-box 2 (SOX2), Kruppel-like factor 4 (KLF4), NANOG, and MYCN." (PMID 25551472, 2014). "We have corroborated our hypothesis with a melanoma cell model as a functional model to demonstrate that, under IH, the PSPC1 increases TGFβ expression and promotes EMT, through TWIST and SLUG transcription factors, as well as CSC, although only by means of SOX2." (PMID 34359789, 2021). "However, mechanisms of stabilizing SOX2 in melanoma have not been interrogated." (PMID 33613844, 2021). "However, in melanoma SOX2 regulation by Usp9x has not been previously reported." (PMID 33613844, 2021). "Thus, the lactate increase observed in SOX2-silenced acidic and non-acidic melanoma cells could be able to contribute to HIF1α expression and glycolytic re-conversion." (PMID 30466459, 2018). "Moreover, the role of ASA in modulating SOX2 expression in melanoma model has not been studied." (PMID 28636992, 2017). "Moreover, Sox2 failed to rescue the migration of Aldh1a1-depleted sh-AhR + sh-Aldh1a1 cells, further supporting a functional interaction between Aldh1a1 and Sox2 in murine melanoma cells." (PMID 26242870, 2015). "This apparent correlation between Sox2 and Aldh1a1 was supported by the observation that ectopic Sox2 expression increased Aldh1a1 mRNA levels in sh-AhR but not in Aldh1a1-interfered melanoma cells, indicating that Sox2 could play a role in maintaining Aldh1a1 expression." (PMID 26242870, 2015). "Interestingly, Sox2 increased Aldh1a1 expression in sh-AhR but not in sh-AhR + sh-Aldh1a1 cells, suggesting that Aldh1a1 and Sox2 may be co-regulated in melanoma cells." (PMID 26242870, 2015). "After a 7-day treatment, stem factors including Nanog, Oct4, and Sox2 were also decreased by 1-5 μmol/L of CHE treatment, indicating that 1-3 μmol/L of CHE decreases stemness of melanoma CSCs without affecting cell viability." (PMID 35761835, 2022). "Usp9x KD but not Usp34 KD reduced SOX2 levels in both BRAF mutant A375, SK-Mel28, and NRAS-mutant SK-Mel147 melanoma cell lines." (PMID 33613844, 2021). "While studies to identify target genes of YAP/TAZ that mediate their activity in VM are lacking in melanoma, in other cancers it was found that YAP/TAZ induce VM by regulating the embryonic stem cell transcription factor SOX2 or by upregulating pro-angiogenic factors such as CYR61 and ANG2." (PMID 38635031, 2024).
melanoma (continued). "We found that pharmacological inhibition of the drug efflux transporter BCRP/ABCG2 with either 1 μM GF-120918 (elacridar) or 5 μM KO-143 led to increased melanoma cell sensitivity to PLX4032 in SOX2-expressing A375 and A2058 cells, without impacting on that of SOX2-depleted cells." (PMID 35944584, 2022). "The stable or transient knockdown of CD271 in melanoma cells revealed that the NCSC-like phenotype is maintained by expression of CD271 which in turn controls the levels of downstream targets, e.g., SOX10, FOXD3, and SOX2 (not shown)." (PMID 32878000, 2020). "While the role of SOX2 has been identified in various cancer models including melanoma, it is not studied whether ASA can modulate SOX2 expression in melanoma model." (PMID 28636992, 2017). "Similarly to SOX2 and unlike the literature, which demonstrates the presence of SOX10 in the cell nucleus, our studies indicated the existence of this protein mainly in the cytoplasm, together with the formation of perinuclear clusters in the studied melanomas." (PMID 41012776, 2025).
colorectal cancer (156 papers, 2012 to 2026). A primary or metastatic malignant neoplasm that affects the colon or rectum. "In multivariable models, SOX2 demonstrated the highest diagnostic performance in colorectal cancer, with an AUC of 0.89 (95% CI: 0.82–0.95), sensitivity of 84% and specificity of 87%." (PMID 40674376, 2025). "Aberrant expression of the pluripotency-associated transcription factor Sox2 is associated with poor prognosis in colorectal cancer (CRC)." (PMID 38473392, 2024). "In some malignancies such as colorectal carcinoma, and lung, stromal SOX2 was found to be linked to a worse prognosis." (PMID 38532463, 2024). "Immunoexpression of transcriptional markers, particularly SOX2, was reportedly associated with the progression of colorectal carcinoma, head and neck cancer, and OSCC." (PMID 37109090, 2023). "The expression of SOX2 has been associated with cancer stem-like properties in skin, bladder and colorectal cancers." (PMID 33471801, 2021). "The results from other research groups also indicated that Sox2 is up-regulated in several types of cancer including colorectal cancer, suggesting it is associated with downstream events of carcinogenesis, including invasion and metastasis." (PMID 29228716, 2017). "Stemness-associated genes NANOG, OCT3/4 and SOX2 are involved in self-renewal activity of colorectal cancer cells." (PMID 27314328, 2016). "Importantly, the increased expression of either SOX2 or nuclear β-catenin have been shown to be associated with distant metastases in colorectal cancer, underlining the importance of these stemness-associated factors for distant spread in this disease." (PMID 26107817, 2015). "Notably, over 90% of cells containing vacuoles stained ß-gal positive, Taken together, these results indicated that Sox2-induced autophagy causes a loss of tumor properties in HCT116 colorectal cancer cells." (PMID 23451179, 2013). "Previous studies have shown that 5‐FU‐resistant colorectal cancer cells exhibit elevated expression of stemness‐associated markers, including NOTCH1, CD44, ALDHA1, Oct4, SOX2, and Nanog." (PMID 41543046, 2026). "Colorectal cancer: SOX2 expression was elevated in 76% of colorectal cancer cases (p < 0.001), with the highest levels observed in patients with advanced tumor stages." (PMID 40674376, 2025). "The AUC was highest for SOX2 in colorectal cancer (AUC = 0.89, sensitivity = 84%, specificity = 87%)." (PMID 40674376, 2025). "SOX2 expression is related to lymph node metastasis and distant metastasis in colorectal carcinomas." (PMID 40104101, 2025). "IGF2BP2 contributed to colorectal cancer pathogenesis and progression by SOX2 m6A methylation and preventing its degradation." (PMID 38714753, 2024). "IGF2BP2 recognizes m6A in the CDS region of SOX2 and prevents its degradation, thereby contributing to the development and incidence of colorectal cancer." (PMID 38384328, 2024). "For SOX2, in colorectal cancer, it acts together with TM4SF1 to promote tumor EMT and maintain its stemness." (PMID 38164286, 2024). "In colorectal cancer, upregulation of the SOX2 gene in colonic stromal cells induces SFRP2 overexpression in cancer-associated fibroblasts, thereby promoting tumor formation." (PMID 39850884, 2024). "Futhermore, loss of miR-638 in vitro promotes cell invasion and mesenchymal-like transition by regulating SOX2 expression in colorectal carcinoma cells." (PMID 38879516, 2024). "In colorectal cancer, radiotherapy activates the PI3K/AKT signaling pathway, which in turn causes upregulation of SOX2 expression, ultimately leading to increased CD44+ cells and enhanced radioresistance." (PMID 37213675, 2023). "The administration of AP or P or AP + P as therapy or prophylaxis in PHZ-induced colorectal cancer significantly downregulated the colonic mRNA expression of CK-20, SOX-2, OCT-4, and NanoG compared to the PHZ group." (PMID 37513415, 2023).